NPY (neuropeptide Y)
Diseases named in the same sentence as NPY in open-access papers (continued):
Sharing a sentence is not in itself a finding about the gene and the disease.
Obesity (continued). "Previous findings suggest that the level of NPY is likely to increase in peripheral neurons and adrenergic receptors due to obesity and metabolic diseases by modulating the level of endocannabinoids and CB1 receptors." (PMID 34466576, 2020). "Reduced circulating PYY and PP as well as elevated NPY levels which can be found in obese subjects give rise to a role in the pathophysiology of obesity." (PMID 33192409, 2020). "Dorsomedial nucleus (DMN) received NPY and melanocyte stimulating hormone (MSH) input from ARC and damage to DMN are associated with hyperphagia and obesity." (PMID 32272767, 2020). "Neuropeptide Y has been shown to modulate mammalian circadian rhythms and there has been interest in its potential for anti-obesity drug development due to increased expression exerting anorexigenic effects." (PMID 31435007, 2020). "In our experiments, as expected, diet-induced obesity led to increased NPY expression both centrally and peripherally, supporting its role in obesity." (PMID 31619003, 2019). "The neuropeptide Y system affects various processes, among others food intake, and is frequently discussed in the context of targeting obesity." (PMID 31533726, 2019). "Transgenic mice overexpressing NPY showed significant obesity and the lipogenic effects as well as inhibition of catecholaminergic tone of NPY were suggested." (PMID 32116676, 2019). "It was found that NPY reduces energy expenditure by decreasing adipose tissue thermogenesis and the obesity of mice was attenuated when NPY was knocked out." (PMID 30348079, 2018). "It was previously reported that NPY expression is induced by inflammatory signals and that this protein participates in obesity-induced adipose tissue inflammation." (PMID 30105036, 2018). "When leptin central signalling is disrupted by genetic modifications, NPY expression increases and POMC expression decreases, putting the organism into an anabolic state, and increasing the risk of obesity." (PMID 30241328, 2018). "Further, conditional deletion of Rb1 in POMC neurons resulted in cell cycle reentry, neuronal apoptosis, and obesity; however, in contrast, deleting Rb1 in the antagonizing AgRP/NPY neurons was well tolerated." (PMID 30185666, 2018). "The treatment of obesity with EA, which was employed to reduce methylation Tsc1 and inhibit the activity of mTORC1, thereby controlling appetite-regulating factors (e.g., NPY, AgRP, and PoMC) and mitigating obesity." (PMID 29853949, 2018). "OE-NPYDβH mice present a genetic obesity model with the metabolic syndrome-like phenotype and with increased peripheral NPY." (PMID 29674968, 2018). "A study revealed that central NPY mRNA levels are high in some obesity models, like after temporary nutritional scarcity, lasting calories restriction, heavy exercise, and seasonal hyperphagia before hibernation." (PMID 28881823, 2017). "NPY is a neuropeptide neurotransmitter in both the brain and the autonomic nervous system which has roles in stress, food intake, obesity, and seizures." (PMID 28861331, 2017). "This neurocircuitry is relevant to the pathogenesis of obesity, since numerous models of obesity and diabetes are characterized by elevated NPY." (PMID 28421037, 2017). "Together, our results demonstrate effects of both genotype and early postnatal environment on obesity of OLETF rats and further suggest an important role of DMH NPY in the development of obesity of OLETF rats." (PMID 28575002, 2017). "NPY has been demonstrated to have critical effects on the development of obesity through promoting appetite and decreasing energy expenditure." (PMID 29109742, 2017). "In leptin-deficient mice, the downstream targets (NPY/AGRP neurons) are therefore constitutively active promoting hyperphagia and resulting in obesity." (PMID 26819774, 2016).
Obesity (continued). "The metabolic effects of prenatal metformin exposure were investigated in a genetic model of obesity, mice overexpressing neuropeptide Y in the sympathetic nervous system and in brain noradrenergic neurons (OE-NPYDβH)." (PMID 27681875, 2016). "In mice with obesity, nuclear factor-κB, glycine receptor subunit alpha-4 (GlyR) and neuropeptide Y levels were elevated, whereas serotonin receptor 1B levels decreased." (PMID 27110685, 2016). "These appetite-related factors (i.e. ghrelin, leptin, AgRP and neuropeptide Y) have been reported to moderate overeating/obesity, affecting the anticipation, consumption, and acquisition of food." (PMID 26754043, 2016). "NPY is a 36-amino-acid peptide neurotransmitter involved in controlling feeding, obesity, and anxiety/stress-related behaviors." (PMID 27684493, 2016). "Analyses of NPY expression levels in juvenile OLETF rats prior to obesity were consistent with such an explanation." (PMID 27512691, 2016). "NPY directly injected into the PVNH caused hyperphagia, reduced energy expenditure, and eventually produced obesity." (PMID 27147943, 2016). "Intracerebroventricular injection and overexpression of Neuropeptide Y (NPY) in the paraventricular nucleus (PVN) has been shown to induce obesity and glucose metabolism disorder in rodents; however, the underlying mechanisms are still unclear." (PMID 25993471, 2015). "Following chronic stress, increased sympathetic release of NPY leads to inflammatory responses, fat angiogenesis, and adipocyte enlargement and proliferation ultimately leading to obesity, and these effects are mediated by Y2 receptors localized in adipocytes." (PMID 25101055, 2014). "The neuropeptide Y (NPY) signaling system is recognized as evolutionarily conserved in animals and regulates several physiological processes such as feeding behavior, obesity, stress, blood pressure, anxiety, memory and circadian rhythms." (PMID 25310341, 2014). "As such, the decrease in NPY in Ptprt−/− mice further suggests the role of PTPRT in nervous system regulating obesity and peripheral insulin resistance." (PMID 24949727, 2014). "In light of the purported systemic role of NPY, it becomes a promising candidate for controlling the development and treatment of obesity." (PMID 24959194, 2014). "The genes NPY and GABRA2 have been previously found associated with obesity and food intake, being involved in multiple central nervous system functions regulation, while TPMT has an important role in drug metabolism." (PMID 24548628, 2014). "This stress paradigm also increases hypothalamic expression of orexigenic peptides such as NPY and Agouti-related peptide, and plasma biomarkers indicative of obesity, an effect that persisted for at least 2 weeks after the stress paradigm was terminated." (PMID 25101055, 2014). "Insulin administration increases POMC mRNA expression while reducing NPY expression and protecting against diet-induced obesity." (PMID 25258479, 2014). "Increased expression of NPY in adipose tissue appears to be a common feature of obesity in different species." (PMID 24959194, 2014). "Consistently, our data show increased NPY secretion in Ptprt+/+ mice that go on to develop obesity and insulin resistance." (PMID 24949727, 2014). "Understanding the role of NPY in energy homeostasis has critical implications for biomedical applications, the most common pharmacological therapies nowadays for obesity involving gastrointestinal surgery and pharmacological interventions." (PMID 24959194, 2014). "While macrophage NPY expression is induced by inflammatory signals and obesity, our results support an anti-inflammatory effect of NPY signals on macrophage and DC maturation." (PMID 23472120, 2013). "BM chimeras generated from Npy−/− donors demonstrated that hematopoietic NPY contributes to the obesity-induced induction of Npy in fat." (PMID 23472120, 2013).
Obesity (continued). "It has also been reported that stress exaggerates diet-induced obesity through a peripheral mechanism in the abdominal white adipose tissue that is mediated by NPY (neuropeptide Y)." (PMID 24344781, 2013). "The best characterized function of NPY in obesity is in the CNS where neuronal NPY stimulates orexigenic pathways via Y1 receptor activation." (PMID 23472120, 2013). "While our results show an anti-inflammatory function of NPY in lean states and mild obesity, previous work suggests a pro-inflammatory role for NPY in response to the combined effects of stress and HFD." (PMID 23472120, 2013). "Overall, our studies suggest that NPY is produced by a range of myeloid cells and that obesity activates the production of NPY in adipose tissue macrophages with autocrine and paracrine effects." (PMID 23472120, 2013). "At the same time, the leptin is still produced but it cannot activate the leptin receptors and restrain obesity and hyperinsulinemia induced by NPY." (PMID 23671868, 2013). "To assess the effects of NPY on adipose tissue inflammation in vivo, we sought to simulate the induction of NPY with obesity with NPY injection." (PMID 23472120, 2013). "In this study, we report the novel finding that the stress hormone NPY is expressed at physiologic levels by adipose tissue macrophages and participates in obesity-induced adipose tissue inflammation." (PMID 23472120, 2013). "Others have shown that stress-induced activation of the NPY system combined with a high-calorie diet results in augmented obesity." (PMID 23118773, 2012). "Conversely, the central application of NPY induces food intake in a number of species, hypolocomotor activity in rats, and can lead to obesity following chronic over-exposure." (PMID 22438946, 2012). "Continuous administration of NPY to the hypothalamus of normal animals results in massive hyperphagia and obesity." (PMID 22768253, 2012). "In our previous mouse study, stress was found to accelerate and amplify the development of high fat diet-induced obesity by up-regulating the release of NPY and the expression of its Y2 receptor (Y2R) within the adipose tissue." (PMID 22570731, 2012). "In general, animal models of obesity present increased expressions of the orexigenic, anti-thermogenic NPY and MCH and reduced expressions of the anorexigenic, pro-thermogenic POMC and CART." (PMID 22279596, 2012). "While ICV injection of NPY into the PVN causes hyperphagia and obesity, destruction of the PVN causes hyperphagia and obesity." (PMID 22899902, 2012). "This makes NPY and its receptors (Y1, Y2, Y4, Y5 and – in mice – y6) possible targets for anti-obesity therapies." (PMID 22768253, 2012). "Estrogens seem to protect female mice from obesity as evidenced for instance by weight gain after gonadectomy, and their effects are at least in part mediated by hypothalamic NPY." (PMID 23118773, 2012). "The findings here reported are important for the design of therapeutic interventions for obesity that include the NPY." (PMID 21799827, 2011). "Our work shows that a moderate overexpression of NPY was sufficient to induce over-feeding, sustained body weight gain and severe obesity in adult rats." (PMID 21799827, 2011). "Our work shows that a moderate overexpression of NPY was sufficient to induce diurnal over-feeding, sustained body weight gain and severe obesity in adult rats." (PMID 21799827, 2011). "For example, central administration of NPY by i.c.v. injection or directly into the PVN induces a robust feeding response and chronic administration of NPY produces continuous hyperphagia, leading to obesity." (PMID 21799827, 2011). "The mechanisms for how saturated fat and sugar-based beverages contribute to human obesity are clearly in rats on an HF choice diet, plasma leptin concentrations and proopiomelanocortin mRNA increased and neuropeptide Y mRNA decreased." (PMID 21235803, 2011).
Obesity (continued). "So far, several pharmacological and genetic studies were performed in order to better understand the role of NPY on feeding behavior and obesity." (PMID 21799827, 2011). "Previously, we showed that established maternal obesity and litter size reduction reciprocally altered hypothalamic NPY and POMC mRNA expression." (PMID 19606226, 2009). "We wanted to establish and compare levels of leptin and NPY in different obesity types in childhood, and to investigate their correlations with auxological parameters." (PMID 17721641, 2007). "Importantly, global knockout of NPY in mice is protective against high fat diet (HFD)‐induced obesity." (PMID 41151834, 2026). "Furthermore, elevated hypothalamic NPY levels in CCK-B receptor–knockout mice have been linked to hyperphagia, increased fat deposition, and obesity." (PMID 40233116, 2025). "The anti-obesity effect could partially be explained by the decreased appetite and food consumption regulated via NPY and GABAB1R." (PMID 39795230, 2025). "In the current study, it can be suggested that EMF triggers anxiety and increases NPY expression, which may trigger a tendency to obesity in male offspring rats." (PMID 40636869, 2025). "The findings suggest that the interplay between DPP-4 and peptides such as PYY, NPY, and PP may play a critical role in the development of obesity- and diabetes-related gastrointestinal complications." (PMID 40142315, 2025). "This extensive connectivity may explain how stress-induced changes in CeA NPY networks contribute to stress-induced obesity." (PMID 40480630, 2025). "Furthermore, NPY has been shown to play a significant role in regulating metabolic homeostasis and energy balance, as observed in condition such as obesity, hypertension, and atherosclerosis." (PMID 40595538, 2025). "Inversely, AgRP/NPY neurons seem to be affected at weaning by different models of maternal obesity." (PMID 40474775, 2025). "NPY is involved in food intake, obesity, and metabolic diseases." (PMID 40179260, 2025). "From 2008 to 2015, “food intake” (burst intensity 6.36), “free radicals” (burst intensity 3.36), “diet induced obesity” (burst intensity 4.82), “body weight” (burst intensity 5.4), and “neuropeptide Y” (burst intensity 3.47) gradually became the most important factors in the study." (PMID 40182755, 2025). "Conversely, elevated substance P and CGRP are associated with migraines and pain sensitization, while high NPY levels may contribute to obesity and metabolic syndrome." (PMID 40001527, 2025). "Similarly, maternal diabetes and obesity also induce hypothalamic changes that result in an imbalance in AgRP/NPY and POMC expression during adulthood." (PMID 40474775, 2025). "In contrast, neuropeptide Y (NPY) contributes to obesity-related OSAS through its involvement in appetite stimulation, fat accumulation via hypothalamic pathways and amplification of hypoxic stress via peptidylglycine α-amidating monooxygenase (PAM)–mediated upregulation during intermittent hypoxia." (PMID 40989139, 2025). "The combination of chronic stress and HFD creates a particularly potent driver of obesity development, yet how this combination influences gene translation and neuropeptide signaling specifically within CeA NPY neurons remains unclear." (PMID 40480630, 2025). "Apart from CGRP, there are other peptides that have been studied to be influenced by age and sex such as the neuropeptide Y, which is also elevated in unhealthy obesity, or the neurofilament light chain, which should be adjusted by age when studying its levels." (PMID 41155252, 2025). "Our findings contribute to understanding the intricate mechanisms governing metabolic regulation via communication between tanycytes and AGRP/NPY neurons in the hypothalamus, which may have potential therapeutic implications for obesity and diabetes." (PMID 40316705, 2025).
Obesity (continued). "Understanding the molecular identity and translational regulation of CeA NPY neurons is crucial for being able to find potential intervention points that may be utilised as anti-obesity targets." (PMID 40480630, 2025). "We then investigated whether mural cells, the postsynaptic targets of NPY+ innervation in iWAT, are also affected by obesity." (PMID 39198648, 2024). "In previous studies, these compounds showed anti-obesity properties that could be explained by different mechanisms, such as modulating neuro-hormones that play a role in satiety, like neuropeptide Y, supressing lipogenesis, or even modifying the microbiota." (PMID 38674834, 2024). "To date, the number of reports on the correlation between asthma, obesity, and NPY is very limited." (PMID 38542187, 2024). "NPY has been shown to play a role in energy metabolism and obesity." (PMID 39033117, 2024). "Under normal conditions, hypothalamic reactive oxygen species (ROS) function to maintain energy homeostasis through balancing the activation between POMC and NPY/AgRP neurons, but excessive ROS would damage these hypothalamic neurons, resulting in disturbed energy homeostasis and obesity." (PMID 38397850, 2024). "NPY is considered a crucial biomarker of metabolic syndromes in obesity." (PMID 38645495, 2024). "Recent findings on NPY neurons targeted genes, particularly antagonists of Y1 and Y5 receptors, compounds, and drugs, must be identified as beneficial agents that can develop for treating obesity." (PMID 38645495, 2024). "At the same time, NPY is strongly involved in appetite regulation, its central administration leads to higher food intake and weight gain, and chronic treatment can result in the development of obesity." (PMID 38542187, 2024). "Here we uncover the mechanism by which NPY in sympathetic neurons protects from obesity." (PMID 39198648, 2024). "Thus the evidence disfavours a pro-obesity role for peripheral NPY, contradicting the current perception." (PMID 39198648, 2024). "Indeed, several studies showed that in individuals with obesity, NPY serum levels are higher compared to lean subjects." (PMID 36830982, 2023). "On the other hand, loss of LepR in POMC/CART, but not AgRP/NPY, neurons in the adult mice promotes obesity only when fed HFD These results suggest that the primary target of leptin is context-dependent." (PMID 37547309, 2023). "Accumulating knowledge on the effect of NPY and its receptor on obesity may provide new insights into the treatment of obese women with PCOS." (PMID 37452264, 2023). "The NPY system is hypothesized to play a key role in regulating energy balance and the pathophysiology of obesity." (PMID 37452264, 2023). "The retained higher ratios of the NPY to POMC neurons born during E12.5 in males may set a tone for male HFD offspring being prone to obesity development in later life." (PMID 37867217, 2023). "In addition to their effects on insulin and leptin, polyphenols have been shown to exert anti-obesity by directly modulating neuropeptides in food intake, as anthocyanins were reported to inhibit neuropeptide Y, suppressing obesity in high-fat diet-fed rats." (PMID 36829976, 2023). "Aberrant methylation of NPY, ADRB3, IGF1, and HIF3a have all been linked to obesity." (PMID 37899888, 2023). "Y1R-preferring NPY analogs with potential therapeutic applications are used to unravel the signaling mediated by this receptor in health and diseases (e.g., cancer, mood disorders, obesity, stress response, food intake)." (PMID 37373115, 2023). "The present study shows that the denervation of rWAT improved bone formation in obese rats mediated by a preferential reduction in neurohormonal actions of NPY, emphasizing the relevance of the adipose tissue–brain–bone axis in the control of bone metabolism in obesity." (PMID 37630764, 2023).